BRAF (B-Raf proto-oncogene, serine/threonine kinase)
Diseases named in the same sentence as BRAF in open-access papers (continued):
Sharing a sentence is not in itself a finding about the gene and the disease.
melanoma (continued). "Critically, MITF re-expression rescued proliferation of melanoma cells when BRAF was depleted using RNAi, or when MEK was inhibited with PD184352." (PMID 18628967, 2008). "This ensures that the levels of MITF are optimal for tumour progression and suggests one reason for why BRAF is such a potent oncogene in human melanoma." (PMID 18628967, 2008). "Critically, in melanoma cells MITF is required downstream of oncogenic BRAF because it regulates expression of key cell cycle regulatory proteins such as CDK2 and CDK4." (PMID 18628967, 2008). "The decrease in MITF protein was due to reduced MITF mRNA expression as determined by quantitative RT-PCR and together these findings clearly demonstrate that in melanoma cells BRN2 is required for MITF expression downstream of oncogenic BRAF." (PMID 18628967, 2008). "Consistent with this, we show that BRN2 and MITF expression occur coincident with oncogenic BRAF in human melanoma samples." (PMID 18628967, 2008). "We propose that its ability to appropriate the regulation of this critical factor explains in part why BRAF is such a potent oncogene in melanoma." (PMID 18628967, 2008). "Here we confirm that BRN2 expression is dependent on ERK signalling downstream of oncogenic BRAF in melanoma cells." (PMID 18628967, 2008). "Although MITF is able to induce cell cycle arrest in melanocytes and melanoma cells in a p16 and p21 dependent manner, MITF gene was found to be amplified in melanoma and its overexpression induced transformation and drug resistance in BRAF mutant melanocytes." (PMID 18211678, 2008). "To corroborate these findings, we used RNA interference (RNAi) to deplete BRAF in melanoma cell lines." (PMID 18628967, 2008). "To further elucidate the role of c-KIT and BRAF in mucosal melanoma, we analysed these two targets in 39 patients with mucosal melanomas treated in our Department." (PMID 19018266, 2008). "Constitutive activity of BRAF is known to be critical for the proliferation and survival of melanoma cells through the activation of the RAF/MEK/ERK mitogen activated protein (MAP) kinase pathway." (PMID 17245336, 2007). "Given the preclinical and clinical evidence supporting a role for oncogenic BRAF in driving melanoma progression, it is unclear why sorafenib 400 mg b.i.d. did not demonstrate significant activity as a monotherapy in advanced melanoma patients." (PMID 16880785, 2006). "The increased apoptosis, observed in human melanoma cell lines when BRAF expression is downregulated using RNA interference, supports a role for oncogenic BRAF-driven MEK/ERK overactivation in maintaining the transformed phenotype of malignant melanoma cells." (PMID 16880785, 2006). "Recent preclinical evidence, showing that blocking V600E BRAF expression promotes apoptosis in human melanoma cells, provided a rationale for targeting signalling through RAF/MEK/ERK in the treatment of melanoma." (PMID 16880785, 2006). "BRAF is a gene that is regulated by RAS binding, and was shown to have missense mutations in 66% of primary melanoma tumours, 59% of melanoma cell lines, and 80% of melanoma short-term cultures." (PMID 12778069, 2003). "Nevertheless, we note that BRAF/MEK inhibition may alter the composition of circulating immune cells in melanoma patients." (PMID 41976295, 2026). "Subjects with biopsy‐accessible BRAF‐mutant advanced melanoma received vemurafenib+/−cobimetinib." (PMID 41514118, 2026). "Cutaneous melanoma samples with HRD had significantly higher prevalence of NF1 mutation (36.06% v 18.5%, P < .001) and significantly lower prevalence of V-RAF murine sarcoma viral oncogene homolog B (BRAF) mutation (48.0% v 37.03%, P < .01)." (PMID 41533995, 2026). "In the PACMEL trial, a Phase I dose‐escalation trial of trametinib in combination with weekly paclitaxel, enrolled 15 melanoma patients without BRAF mutations." (PMID 41492362, 2026).
melanoma (continued). "Another randomized Phase III (IMspire170, NCT03273153) compared cobimetinib plus atezolizumab (PD‐L1 inhibitor) with single agent of pembrolizumab in patients with BRAF wild‐type melanoma (n = 71; 32% of combination group and 46.4% of pembrolizumab group with NRAS mutation)." (PMID 41492362, 2026). "In the group of ipilimumab plus nivolumab, mPFS was significantly higher for melanoma with BRAF mutation (9.9 months; 95% CI, 6.8–17.2 months) compared with NRAS‐mutant (4.8 months; 95% CI, 3.0–7.5 months) and BRAF/NRAS wild‐type (5.3 months; 95% CI, 3.6–7.1 months)." (PMID 41492362, 2026). "Immune checkpoint inhibitors (ICIs, e.g., antiprogrammed cell death protein 1 [PD-1]) and targeted therapies (e.g., BRAF/MEK inhibitors) have revolutionized treatment for melanoma patients (MPs), but prognostic markers of drug response and disease progression remain elusive." (PMID 41866888, 2026). "The Phase III IMspire150 study compared mPFS in vemurafenib and cobimetinib with or without atezolizumab for advanced BRAF mutation melanoma." (PMID 41492362, 2026). "have identified that SCH772984 (ERK1/2 inhibitor) may help overcome the resistance of BRAF‐mutant melanoma to BRAF or MEK inhibitor." (PMID 41492362, 2026). "Point mutations or gene fusions in other genes (e.g., mutations in BRAF, KRAS, APC, and MET genes, or gene fusions in ZEB2‐ALK and SOX5‐RAF1 genes) may be associated with melanoma proliferation or melanoma progression in satellite nevi or LCMN." (PMID 41474606, 2026). "dabrafenib is a BRAF inhibitor used in the treatment of advanced melanoma." (PMID 41561226, 2026). "Our data support prior studies showing increased TIL at 1–2 weeks after BRAF/MEKi therapy for advanced melanoma and extend those findings by showing that this increase in TIL persists in most patients through the first month, including both CD8 and CD4 T cells." (PMID 41514118, 2026). "Advanced melanoma remains difficult to treat due to its intrinsic resistance to conventional therapies and the frequent development of acquired resistance to targeted agents, such as BRAF inhibitors." (PMID 41751773, 2026). "This raises the possibility that combining adoptive T cell therapy or cancer vaccines with BRAF/MEKi may be valuable for such patients to support clonal expansion in the TIME of melanoma‐reactive T cells." (PMID 41514118, 2026). "In melanoma, BRAF/MEK inhibition and immunotherapy might be able to delay the onset of BM, although prospective data remains limited to date." (PMID 41928334, 2026). "Resistance to BRAF inhibitors in melanoma may arise from abnormal changes induced by RNA methylation that affect BRAF mRNA splicing." (PMID 41362736, 2026). "Intracranial hemorrhage may result from the combination of stereotactic radiotherapy and BRAF/MEKi, but could also reflect the inherent hemorrhagic tendency of melanoma." (PMID 41533377, 2026). "Although dabrafenib/trametinib (D+T) target the BRAF/MAPK pathway and show efficacy in BRAFV600E mutant melanoma, their effectiveness against GBM remains unclear." (PMID 42195328, 2026). "Rapid cSCC develops in melanoma patients on BRAF inhibitors due to paradoxical MAPK activation." (PMID 41507151, 2026). "Moreover, pan-RAF inhibitors, such as belvarafenib, when combined with MEK inhibitors (cobimetinib), have promising but limited efficacy in non-BRAF-mutant melanomas." (PMID 42091854, 2026). "Trametinib, a selective MEK1/2 inhibitor targeting the Mitogen-Activated Protein Kinase (MAPK) signalling pathway, is approved for BRAF V600 mutant melanoma but may also show activity in tumours with other alterations." (PMID 41664938, 2026). "More than half (53.3%) of nevus–melanoma pairs shared identical MAPK driver mutations, consistent with prior sequencing studies showing that benign nevi frequently harbor BRAF or NRAS mutations and that a substantial fraction of melanomas retain the same driver mutation as their precursor." (PMID 41516405, 2026).
melanoma (continued). "Similarly, in melanoma, treatment with MAPK inhibitors elevates FAK activation in human BRAF V600E melanoma cells, suggesting that FAK activation represents an intrinsic resistance mechanism triggered by MAPK inhibition." (PMID 41537447, 2026). "Furthermore, we and others have demonstrated that BRAF-/MEK-targeted therapies for the treatment of advanced melanoma induce AR expression in males and females; however, treatment outcomes are worse in male patients." (PMID 41486951, 2026). "In a recent phase II study in patients with advanced melanoma who harbored an HR mutation, niraparib, a PARPi, demonstrated a disease control rate of 64% and a median PFS of 16 weeks in patients who progressed on PD-1 blockade or BRAF/MEK inhibition." (PMID 41533995, 2026). "ICMT knockdown inhibited proliferation of BRAF-inhibitor-resistant melanoma cells." (PMID 42127111, 2026). "AR upregulation is a key adaptive mechanism in BRAF-mutant melanoma." (PMID 40940929, 2025). "This suggests that canonical Wnt signaling may directly contribute to metabolic mitochondrial reprogramming via regulation of MITF-mediated effects on mitochondrial biogenesis in BRAF mutant melanomas." (PMID 40558548, 2025). "In exceedingly difficult cases, molecular and genomic analysis can also be beneficial, as melanoma arising in blue nevi do not typically exhibit BRAF mutations, but rather GNAQ, GNA11, PLCB4, or CYSLTR2 mutations." (PMID 40843873, 2025). "In the presence of a RIP3K mutation, the BRAF inhibitor Dabrafenib, unlike Vemurafenib, suppresses necroptosis in melanoma cells." (PMID 40331942, 2025). "However, it should be noted that BRAF/MEKi combination therapies are the standard of care for BRAF V600-mutant metastatic melanoma, which accounts for approximately 40–50% of all melanoma cases." (PMID 40507236, 2025). "The development of selective BRAF V600 inhibitors (BRAFi), which specifically target the mutated BRAF protein, and their subsequent combination with MEK inhibitors (MEKi) has substantially improved outcomes in advanced melanoma." (PMID 41294692, 2025). "These targets are central mediators of adaptive survival and dedifferentiation in BRAF^V600E melanoma, suggesting that CST not only restrains tumor growth but may re-sensitize resistant cells to existing therapies." (PMID 41279995, 2025). "Based on these findings, TRE, whether administered alone or alongside siRNA targeting BRAF, cannot be considered a viable treatment strategy for melanoma." (PMID 41170188, 2025). "Accumulating evidence has shown that ER stress-induced autophagy may be a potential pro-survival mechanism contributing to melanoma development and resistance to BRAF inhibitors." (PMID 40932870, 2025). "Moreover, the overexpression of receptor tyrosine kinases (RTKs), such as EGFR, provides melanoma cells with alternative proliferative signals that enable them to circumvent the inhibitory effects of BRAF and MEK inhibitors." (PMID 39897423, 2025). "Taken together, the preclinical efficacy in the AGK::BRAF fusion melanoma model, and the fact that tovorafenib has been approved for relapsed/refractory pLGGs, supports tissue agnostic activity for tovorafenib in tumors harboring BRAF fusions or rearrangements." (PMID 40111124, 2025). "NRAS-mutant melanomas demonstrate aggressive clinical behavior and pose significant therapeutic challenges, as effective targeted therapies remain elusive compared to their BRAF-mutant counterparts." (PMID 40563669, 2025). "In addition, FAO is enhanced when melanoma cells receive long-term BRAF inhibitor treatment, and inhibition of FAO by ranolazine can improve the efficacy of anti-PD-L1 treatment." (PMID 40514365, 2025). "Additionally, BRAF V600E mutation activates the Oct-HMGCL-acetoacetate axis and MEK–ERK signaling, enabling melanoma cells to use ketone bodies as a metabolic substrate." (PMID 40565936, 2025). "Importantly, these four adaptive programs were conserved across the independent BRAF-mutant melanoma models." (PMID 41000875, 2025).
melanoma (continued). "BRAF, NRAS, or NF1 mutations can co-occur with C/T mutations in the promoter region of the telomerase reverse transcriptase (TERT) gene, which are frequently observed in melanoma, occurring in 30–85% of cases depending on disease stage." (PMID 39859576, 2025). "The efficacy of approved small-molecule inhibitors in melanoma is primarily determined by the presence of actionable mutations—most notably BRAF V600 and activating KIT alterations—rather than by the tumor’s anatomical site alone." (PMID 41302945, 2025). "In contrast, oncogenic NRAS mutations, which do not co-occur with BRAF mutations, are present in approximately 15–25% of melanoma cases." (PMID 39859576, 2025). "A BRAF mutation suggests that the lesion is more likely a conventional melanoma with spitzoid features rather than a true SM." (PMID 40227833, 2025). "Thus, Cobi+Reg produced marked antitumor efficacy in multiple PDX lines encompassing the major molecular subtypes of melanoma (i.e., BRAF-, NRAS-, and NF-1–mutant) developed after progression on PD-1–based ICB." (PMID 40638246, 2025). "Following progression after cessation, a second course of ICI could be considered a reasonable option, especially in the context of limited therapeutic choices in patients with BRAF-wild type melanomas." (PMID 39958328, 2025). "This is notably evident in BRAF V600E mutations, where response to treatment varies by tumor type—requiring monotherapy in some cancers, a combination with MEK inhibitors in melanoma, and a combination with EGFR inhibitors in CRC to counteract feedback activation pathways and inherent resistance." (PMID 40576713, 2025). "However, BRAF inhibitor resistance, as well as the low response of other non-melanoma cancers, e.g., BRAF-mutant CRC, limits the clinical application of these promising drugs." (PMID 39935431, 2025). "In melanoma harboring the oncogenic BRAFV600E mutation, KSR1 knockout impaired cell proliferation, induced cell cycle arrest, and promoted apoptosis, highlighting a context-dependent synthetic vulnerability in BRAF-driven tumors." (PMID 41155983, 2025). "AXL functions as an upstream regulator of AKT-mediated resistance to BRAF inhibitors in melanoma with wildtype PTEN, while AKT and Fascin regulate each other, creating potential feedback mechanisms that may stabilize the pro-metastatic state." (PMID 41286309, 2025). "While antioxidants may slow tumor progression in specific cancers such as MYC-driven lymphoma, they can accelerate tumor growth, metastasis, and angiogenesis in other settings, including KRAS-driven lung cancer and BRAF-driven melanoma." (PMID 40646353, 2025). "Targeting RAC1 activity via genetic disruption of PREX2 can enhance sensitivity to MAPK inhibition in BRAF-V600E–driven melanoma in vivo, although pharmacologic targeting of the RAC1 effector p110β also seems capable of enhancing responses to MAPK inhibition in vitro." (PMID 39636745, 2025). "Furthermore, mutations in two genes of the mitogen-activated protein kinase, BRAF and NRAS, have been implicated in 80% of melanoma cases." (PMID 41280706, 2025). "Forty-six percent of patients had BRAF V600E/K-positive melanoma." (PMID 40733704, 2025). "For patients with BRAF-mutant melanoma, combination treatment with BRAF inhibitors plus MEK inhibitors (BRAFi + MEKi) leads to tumor shrinkage in the majority of patients but tumors progress, with a median progression-free survival (PFS) of approximately 14 months." (PMID 40955663, 2025).
melanoma (continued). "Kinase inhibitors targeting oncogenic v-Raf murine sarcoma viral oncogene homolog B1 (BRAF) genes are also associated with a high ORR and improved survival for patients with advanced melanoma when received as a monotherapy or in combination with mitogen-activated protein kinase (MEK) inhibitors." (PMID 40552935, 2025). "Similarly, MEK inhibitors like trametinib have shown considerable improvements in progression-free survival (PFS) and overall survival (OS) when combined with BRAF inhibitors, representing a paradigm shift in melanoma treatment." (PMID 40861441, 2025). "BRAF mutations are not as common in bladder cancer as other types of cancers such as melanoma or colorectal cancer." (PMID 39857950, 2025). "Vemurafenib-resistant v-Raf murine sarcoma viral oncogene homolog B1 (BRAF)-mutant melanomas activate mitogen-activated protein kinase (MEK)/extracellular signal-regulated kinase (ERK) signaling to increase GLUT1/3 and HK2 expression, enhancing glucose uptake and glycolytic flux." (PMID 40725147, 2025). "Similarly, a direct link between CAF-derived NRG1 and the promotion of therapy resistance via ErbB3 receptor signaling was observed in BRAF-mutant melanoma and prostate cancer." (PMID 40524253, 2025). "Future studies are warranted to clarify whether strategies that modulate NR2F1 activity, either through inhibition or agonism, could confer clinical benefit in the context of BRAF-mutant melanoma." (PMID 40955667, 2025). "Tiago and colleagues’ analysis of published single-cell and bulk transcriptomics datasets confirmed that NR2F1 was highly expressed in BRAFi + MEKi–treated patients with melanoma and BRAF-mutant melanoma patient–derived xenografts, particularly in invasive MRD, as well as in preclinical cell models." (PMID 40955667, 2025). "Furthermore, exposure of BRAF V600E melanoma cells to sublethal doses of BRAF and MEKi induces a shift toward a drug-tolerant state." (PMID 40872623, 2025). "Research shows that in the radial growth phase, i.e., the early phase, of melanoma formation, the mutation rate in BRAF is as low as 10%, suggesting that it is not crucial for melanoma initiation." (PMID 39859464, 2025). "To demonstrate the hypothesis, we further characterized glutamine metabolism in melanoma cell lines (with mutations on BRAF, NRAS, or cKIT) that are resistant to RTKi/MAPKi and in tumor samples from melanoma patients." (PMID 40943167, 2025). "In mice bearing melanoma PDX tumors harboring an AGK::BRAF fusion, tumor regression was observed in response to oral administration of tovorafenib for 14 days at dosage levels of 25 and 17.5 mg/kg daily assessed in two separate efficacy studies, respectively (respectively)." (PMID 40111124, 2025). "Of new melanomas diagnosed, 14% (n = 13 138/91 415) had a BRAF test registered and 1% (n = 126/13 138) had failed, inconclusive or unknown test results." (PMID 40902091, 2025). "Consequently, current clinical evidence strongly supports initiating treatment with immunotherapy before considering targeted therapy in metastatic BRAF-mutant melanoma." (PMID 40332392, 2025). "This included the melanoma driver mutations NRAS Q61K/R, BRAF V600E, CDKN2A P114L, and HRAS G13." (PMID 40075679, 2025). "Vemurafenib and dabrafenib are FDA-approved BRAF inhibitors (BRAFi) for treating non-resectable melanomas with V600E/K BRAF mutation." (PMID 40558548, 2025). "Overall, these findings suggest that ganetespib could serve as an effective therapeutic option, both as a monotherapy and in combination, for treating BRAF(V600E)-mutant melanoma, particularly as a strategy to overcome acquired resistance to selective BRAFi." (PMID 40872623, 2025). "Thus, BRAF-positive melanoma cells that remained viable after exposure to vemurafenib exhibited characteristics of senescent tumour cells and increased adhesive properties due to fibronectin binding." (PMID 40636307, 2025).